CCND1 (cyclin D1)
Diseases named in the same sentence as CCND1 in open-access papers (continued):
Sharing a sentence is not in itself a finding about the gene and the disease.
tumor (continued). "The GU‐Uro tumours differed from Uro tumours by increased proliferation, immune and extracellular matrix (ECM) mRNA signatures, but protein expression levels of the canonical Uro genes FGFR3, CCND1 and TP63 were not different in the Uro versus GU‐Uro groups of tumours." (PMID 28195647, 2017). "Interestingly, we also found that the cyclin D1 expression was significantly increased in HCC tumor tissues without HBV infection, supporting the notion that the expression and function of cyclin D1 in HCC without HBV infection was different to that with HBV infection." (PMID 25851350, 2015). "Cox proportional hazards analysis showed that adenocarcinoma patients with cyclin D1 overexpression were found to have a 1.87 (95 % confidence interval = 1.12 – 2.69, P = 0.02) times poorer RFS than those without, after adjusting for age, tumor size, pathologic stage, and cyclin E expression." (PMID 26681199, 2015). "Thus, proliferative markers like pHH3 but not cyclin D1 show a progressively increased expression from PMC and encapsulated FVPTC to lesions with metastatic potential, lending them a predictive prognostic value, even though PTC has been reported to be an indolent tumor with low proliferation rates." (PMID 26863116, 2016). "Likewise, western blotting suggests that p-Akt(Ser473) correlates with cyclin D1 expression in P-NET, suggesting that these signaling pathways are actively promoting cell proliferation in these cancers, although cyclin D1 did not relate to tumor aggressiveness." (PMID 26793165, 2015). "One possible explanation for the lack of 11q13 amp in HPV-positive tumours may be that amplification of chromosomal band 11q13 might be unnecessary, as the resulting interaction of the HPV E7 oncoprotein with pRb might allow the cells to be less dependent on CCND1 for cell cycle progression." (PMID 17003776, 2006).
cancer (2,559 papers, 1997 to 2026). A tumor composed of atypical neoplastic, often pleomorphic cells that invade other tissues. "Cyclin D1 is a key regulator of cell cycle progression and has been implicated in the initiation and progression of various cancers." (PMID 41465498, 2025). "The CCND1 gene encodes cyclin D1, a proto-oncogene that plays a crucial role in the progression and metastasis of multiple cancers, including HCC." (PMID 40699663, 2025). "This alteration is in line with research showing that DZN inhibits the production of cyclin D1 and Bcl-2, which causes cancer cells to undergo cell cycle arrest and apoptosis." (PMID 40217305, 2025). "Cyclin D1, encoded by CCND1, is a critical regulator of the cell cycle, contributing to uncontrolled cellular proliferation in cancer." (PMID 39789065, 2025). "Network 5 displayed a notable link to CCND1, which is associated with cancer progression and metastasis." (PMID 40408428, 2025). "For instance, miRNAs such as the miR-17-92 cluster and miR-26a have been implicated in regulating components of the SMAD4/C-MYC/Cyclin D1 axis in other cancer types." (PMID 40224178, 2025). "The same study also indicated that WFA treatment decreased the expression of CCND1, a cell cycle oncogene associated with increased cell proliferation in cancers." (PMID 39940977, 2025). "For example, piR-651, piR-52200, and piR-34971 have been shown to be upregulated in NSCLC, with piR-651 linked to cancer progression, potentially through regulation of cell cycle control proteins such as cyclin D1 and CDK4." (PMID 40949873, 2025). "The CCND1 gene --encoding cyclin D1-- shows some of the highest frequency of amplification and overexpression among cancer genes across a broad spectrum of human tumors." (PMID 40272409, 2025). "Misrepresentation of the CCND1 gene encoding cyclin D1 and overexpression of cyclin D1 protein have commonly been found in various malignant neoplasms." (PMID 40051490, 2025). "Activation of ERα permits the expression of factors such as MYC and CCND1, which have oncogenic potential and increase the risk of cancer cell proliferation and DNA damage in response to estrogen." (PMID 40708058, 2025). "For example, cytoplasmic membrane-associated cyclin D1 fosters invasiveness and metastasis in cancers, while mitochondria-localized cyclin D1 alters glucose metabolism." (PMID 40076565, 2025). "The importance of this pathway in cancer is underscored by its frequent subversion through cyclin D1 overexpression or loss of inhibitors such as p16." (PMID 41226361, 2025). "MYC and CCND1 have been well-associated with cancer through many studies, and their respective proteins play important roles in the cell cycle." (PMID 40770488, 2025). "Deregulation of Cyclin D1 can lead to uncontrolled cell proliferation and is often associated with cancer." (PMID 39858466, 2025). "Multiple clinical studies demonstrated that dysregulation of CCND1 is associated with poor prognosis and platinum-based chemotherapy response in various human cancers, highlighting its potential as a tumor predictive biomarker." (PMID 38589850, 2024). "After adjusting for age and sex, the association between CCND1 rs9344 polymorphism and cancer risk was analyzed in additive, dominant and recessive models, respectively." (PMID 38589850, 2024). "Uncontrolled cell proliferation is a key hallmark of cancer and is achieved through several mechanisms, including elevated levels of cyclin D1 expression." (PMID 38238702, 2024). "The dysregulation of cyclin D1 function or gene expression causes a loss of normal cell cycle control during cancer development." (PMID 38473336, 2024). "In this study, we conducted a comprehensive pan-cancer analysis to determine CCND1's diagnostic function and prognostic significance in a number of cancer types." (PMID 39188436, 2024). "The presence of a large number of mutations in CCND1 is closely related to cancer onset, progression, prognosis and treatment." (PMID 39739897, 2024).
cancer (continued). "Although several of the identified oncogenes such as MYC, ETV1, and CCND1 have been previously linked to enhancer hijacking, we identified their novel hijacked enhancers that are cancer type specific." (PMID 39033128, 2024). "The investigation of clinical parameters revealed associations between CCND1 expression and factors such as age, gender, race, and cancer stage." (PMID 39188436, 2024). "These genes, including Smc2, Mcm3, Ccnd1, Rasal2, Mcm6, and Mad2l1, are linked to cancer progression and metabolic regulation." (PMID 39272991, 2024). "Cyclin D1 (CCND1) plays a pivotal role in cancer susceptibility and the platinum-based chemotherapy response." (PMID 38589850, 2024). "CCND1 is a cell cycle regulatory protein, playing a vital role in the transition from the G1 to S phase of the cell cycle, studies have shown that mutations or overexpression of the CCND1 gene are associated with the occurrence and development of cancer." (PMID 39157338, 2024). "Although CCND1 amplification has been proposed as major alterations in cancer genomes, we observed both missense mutations and indels of CCND1 were associated with PTEN mutation contexts." (PMID 39160568, 2024). "The cancer susceptibility was higher in ADC patients with CCND1 rs9344 AA genotypes than in those with GG and GA genotypes (adjusted OR = 1.755, 95%CI = 1.057–2.912, P = 0.030)." (PMID 38589850, 2024). "There are a large number of mutations in CCND1, which are closely related to the occurrence, development, prognosis, and treatment of cancers." (PMID 37024471, 2023). "Currently, more than 4000 mutations are discovered in CCND1 by the Catalogue of Somatic Mutations in Cancer and dbSNP databases." (PMID 37024471, 2023). "CCND1 is often overexpressed in a variety of cancers and is associated with tumorigenesis and metastasis, and its loss is sufficient to induce G1 cell cycle arrest." (PMID 36588153, 2023). "Alternative splicing of CCND1 pre-mRNA is one of the oncogenic splicing events and is closely associated with the dysregulated cell cycle in cancer cells." (PMID 37024471, 2023). "In recent years, an increasing number of studies have found that CCND1 gene polymorphism was also associated with the occurrence and development of cancers, especially to chemotherapy response of cancers." (PMID 36915230, 2023). "IL-6 acts directly on cancer cells to induce the expression of STAT3-encoding proteins driving cancer proliferation, i.e., cyclin D1 and survival, i.e., BCL2-like protein 1 (BCL-xL)." (PMID 37480115, 2023). "A hyperactivation of Wnt/β-catenin signaling has often been observed in cancer, this pathway regulates the cyclin D1 expression and histone acetylation and it is linked to the transduction of mechano-physical signals." (PMID 38046276, 2023). "Accordingly, this mutation‐drug association is being tested in an ongoing phase II pan‐cancer trial (NCT04439201) to assess the efficacy of palbociclib in patients with various malignancies harbouring CCND1/2/3 amplifications." (PMID 36670542, 2023). "CCND1 isoforms are associated with disease risk and/or clinical outcome in cancers, and can be used to some extent to predict cancer risk, clinical prognosis, or therapeutic response." (PMID 37024471, 2023). "Previous studies reported that CCND1 G870A polymorphism was associated with chemotherapy drug response in cancers." (PMID 36915230, 2023). "According to The cBioPortal for Cancer Genomics database analysis of samples with mutation data in pan-cancer (TCGA PanCancer Atlas Studies), the mutation frequency of CCND1 in patient is 6%." (PMID 37024471, 2023). "Emerging evidence has pinpointed a pivotal role of dysfunctional E3 ubiquitin ligase in the cancer-associated cyclin D1 accumulation." (PMID 37414783, 2023). "CCND1 has been shown to participate in regulating DNA damage repair, which is associated with chemoresistance in cancer." (PMID 36980210, 2023).
cancer (continued). "The dysregulation of cyclin D1 expression or CDK4/6 activation can directly lead to some of the hallmarks of cancer upregulation via causing proliferation or overriding of checkpoints." (PMID 37427143, 2023). "Consistently, MG53 deficiency results in accumulation of cyclin D1 protein and accelerates cancer cell growth both in culture and in animal models." (PMID 37414783, 2023). "Consistent with its function as an oncogene, CCND1 levels are elevated in multiple cancers, including HCC, and are associated with poor prognosis and tumor recurrence." (PMID 36980210, 2023). "We found a reverse relationship between the cyclin D1 expression and the stiffness of the 3D cancer cell system, and this expression was also associated to variation of the histone H3 acetylation." (PMID 38046276, 2023). "The claudin-low/non-ER-negative/HER2-negative group had a higher prevalence than claudin-low/ER-negative/HER2-negative cancers of amplifications in loci 11q13.3, 17q12 and 8p11.23, encoding for the genes CCND1, ERBB2 and NSD3, respectively." (PMID 37345027, 2023). "The altered regulation of cyclin D1 has been implicated in the progression of various cancers, including breast, esophagus, bladder, and lung cancers." (PMID 37375411, 2023). "Cyclin D1 with CDKs promotes cell cycle progression, and its overexpression is linked to the development of cancer." (PMID 37242455, 2023). "Through analysis of differential methylation profiling, CCND1, responsible for encoding cyclin D1, emerged as a potential cancer-driving gene in these tumors due to the distinctive hypermethylation of the CCND1 promoter observed specifically in GCTBs." (PMID 37686526, 2023). "Actually, cyclin D1 is highly expressed and/or mutated in various cancers and is considered as a proto-oncogene." (PMID 36765917, 2023). "Cyclin D1 (CCND1), a crucial mediator of cell cycle progression, possesses many mutation types with different mutation frequencies in human cancers." (PMID 37024471, 2023). "NF-κB-dependent cancer-relevant genes mostly encode for cytokines, cell cycle genes like cyclin D1, matrix metalloproteinases (MMPs) and anti-apoptotic proteins." (PMID 36899924, 2023). "Cyclin D1-specific E3 ubiquitin ligase mutations result in the accumulation of cyclin D1 in cancer cells." (PMID 37427143, 2023). "Cyclin D1 overexpression is linked with the development and progression of cancer, and low cyclin D1 levels inhibit cell cycle progression and, thus, cell proliferation." (PMID 37242455, 2023). "The cyclin D1 gene (CCND1) has been demonstrated to be upregulated in PCa and is associated with cancer progression and poor prognosis in PCa patients." (PMID 35668070, 2022). "Common single nucleotide polymorphism (SNP) in the CCND1 gene (rs9344) G870A is associated with the increased risk of cancer." (PMID 35626215, 2022). "On the other hand, such kind of inhibition induced by eL31 depletion led to the downregulation of cancer-associated elements P-Akt, CCND1, CDK6 and PIK3CA." (PMID 36309731, 2022). "While Rb itself is inactivated in some cancer types, several of its upstream regulators, including p16INK4a, cyclin D1, and CDK4, are more commonly mutated resulting in compromised Rb function." (PMID 35814428, 2022). "The down-regulated expression of cyclin D1 and up-regulated expression of CDKIs can reduce CDKs’ activities and cause cell cycle arrest, which prevents cancer cell proliferation." (PMID 35804655, 2022). "Upregulation of CCND1 is associated with tissue differentiation, metastasis, and poor survival in cancer patients." (PMID 36313570, 2022). "As the next step, KNTC1 knockdown caused some cancer-associated factors P-Akt, CCND1, c-Myc, CDK1 and PIK3CA depletion." (PMID 35933405, 2022). "As expected, CCND1 was one of the top oncogene candidates identified in MCL tumors confirming previous studies for constitutive overexpression of CCND1 as an initial cancer-associated alteration that promotes uncontrolled proliferation." (PMID 36359790, 2022).
cancer (continued). "Our results concerning allele A as the factor increasing the risk of the LC are consistent with recently published meta-analysis investigating the association between the G870A CCND1 polymorphism and cancer in the upper aerodigestive tract." (PMID 35626215, 2022). "The Thr-286 mutations have been identified in human cancer specimens, and importantly, the tumorigenic isoform of cyclin D1, cyclin D1b, is also found in human cancers from esophagus, breast, lung, and prostate as well as in lymphoma." (PMID 35565262, 2022). "CCND1 gene encodes Cyclin D1 protein, the alternations and overexpression of which are commonly observed in human cancers." (PMID 35626215, 2022). "Given the frequent over-expression of Cyclin D1 in cancer cells, its expression appears to be closely linked with carcinogenesis." (PMID 35720292, 2022). "We examined the expression of two well known STAT3 downstream target genes implicated in anti-apoptotic (Bcl-xL) and proliferative (Cyclin D1) cancer cell activities after treatment with mc-1Stat3 or dc-Stat3." (PMID 35847174, 2022). "Curcumin also inhibited cyclin D1 and caused cell-cycle disruption in the G1 phase of the same cancer cell line, according to." (PMID 35530318, 2022). "One of the essential functions of Akt during cancer cell proliferation is the aggregation of the cyclin D1 protein, which is mainly regulated by the loss of kinase activity of GSk-3b due to Akt phosphorylation." (PMID 36160435, 2022). "Cyclin-D1 is a cell cycle control protein and has been linked to the development and progression of cancer." (PMID 35204839, 2022). "Cyclin D1 activity is normally intensified in cancer; therefore, cancers showing overexpression of cyclin D1 are susceptible to GSK-3β activation." (PMID 35807651, 2022). "Loose of the cell cycle regulation is central to this oncogenic proliferation, and dysregulation in markers (such as E2F1, PLK1, CCNE1, and CCND1) associated with cell cycle mechanism is one of the most prominent molecular aberrations in all cancers." (PMID 35419294, 2022). "We observed an enriched CCND1 mutation in premalignant disease state and discovered cancer-associated fibroblast cells harboring pro-stemness properties." (PMID 35087207, 2022). "Their appearance has been implicated in cancer-specific super-enhancer hijacking at a number of oncogenes (including CCND1)." (PMID 35863900, 2022). "Oncogenic β-catenin has been implicated in cancer initiation, growth and metastasis due to its ability to transcriptionally deregulate the expression of multiple genes, with CCND1 and MYC as prominent examples." (PMID 34389725, 2021). "Oncogene cyclin D1 has been found overexpressed in human cancers and implicated in many activities, such as cell cycle promotion, chromosomal instability, mitochondrial function and cellular senescence." (PMID 34900704, 2021). "Cyclin D1 is overexpressed in several human cancers, and loss of cyclin D1 reduces damage-induced RAD51 focus formation, impairs HR repair, and sensitizes cancer cells to chemotherapeutic agents." (PMID 34440403, 2021). "The overall impact of these missense SNPs on post-translational modification of Cyclin D1 can be stated as R15S and A190S can cause a gain of serine phosphorylation sites and loss of methylation function which can lead to cancer progression." (PMID 33438725, 2021). "Sustained oxidative stress increases the risk of cancer development either through inducing mutagenesis or by promoting the expression of proto-oncogenes such as cyclin D1." (PMID 33789681, 2021). "Cyclin D1 functions as a checkpoint at G1/S phase transition, decreased percentage of Cyclin D1 expression is associated with cancer cells apoptosis." (PMID 33568044, 2021).